RBP4 (retinol binding protein 4)
Diseases named in the same sentence as RBP4 in open-access papers (continued):
Sharing a sentence is not in itself a finding about the gene and the disease.
breast carcinoma (18 papers, 2014 to 2025). "For example, altered expression of RBP4 has been associated with poor prognosis in several cancers, including breast cancer, gastric cancer, and hepatocellular carcinoma." (PMID 41301068, 2025). "Such analyses conducted in patients with breast cancer suggested a link between elevated RBP4 and the risk of breast cancer." (PMID 32156052, 2020). "In this study, we also analyzed the association between serum RBP4 levels and clinical characteristics among breast cancer patients." (PMID 28002423, 2016). "In other words, it is hard to define the causal relationship between serum RBP4 levels with breast cancer." (PMID 28002423, 2016). "Dietary pattern have been closely related to the risk of breast cancer, while dietary intake of many nutrients can affect serum RBP4 concentration." (PMID 28002423, 2016). "Whereas, serum RBP4 levels were positively associated with breast cancer risk among subjects with lower BMI (<25 kg/m2) (multivariable OR = 2.72, 95% CI = 1.09 to 6.79 for second versus lowest tertile)." (PMID 28002423, 2016). "We performed a case-control study to evaluate the association between serum RBP4 levels and the risk of breast cancer." (PMID 28002423, 2016). "In this current case-control study, we observed a positive correlation between the levels of serum RBP4 and breast cancer risk, especially among patients with lower BMI." (PMID 28002423, 2016). "Subjects in the second RBP4 tertile also revealed increased risk of breast cancer and the OR is 2.03(P <0.05)." (PMID 28002423, 2016). "Further investigation is merited to corroborate our findings and to elucidate the underlying molecular mechanism between RBP4 and breast cancer." (PMID 28002423, 2016). "Regarding retinol-binding protein 4, the low expression of Rbp4 has previously been associated with a poorer prognosis in patients with renal cell and hepatocellular carcinomas or breast cancer." (PMID 36430209, 2022). "In addition, we also investigated the association between serum RBP4 levels and clinicopathological features of breast cancer." (PMID 28002423, 2016). "Thus, we further conducted a stratified analysis by BMI, and the results indicated that breast cancer risk have a positive association with second tertile of serum RBP4 level in lower BMI subgroup(BMI <25kg/m2)." (PMID 28002423, 2016). "Our result revealed that the serum level of RBP4 was significantly higher in patients with ER or PR negative than those with ER or PR positive, which indicated that high serum RBP4 levels could be a risk factor for poor prognosis of breast cancer." (PMID 28002423, 2016). "When the model was further adjusted for potential risk factors of breast cancer, the results were similar, with ORs (95% CIs) of 2.16(1.01–4.61) and 2.07(1.07–4.00) for women in the second and highest RBP4 tertile, respectively, when compared to those in the lowest tertile(P <0.05)." (PMID 28002423, 2016). "Similarly, our results showed a strong positive association between circulating RBP4 levels and breast cancer risk." (PMID 28002423, 2016). "Our results for the first time suggested serum RBP4 levels could be associated with the risk of breast cancer." (PMID 28002423, 2016). "Hence, the purpose of the present study was to determine whether high levels of serum RBP4 are associated with an increased risk of breast cancer using a case–control study." (PMID 28002423, 2016). "Although previous researchers had investigated RBP7 in breast cancers, our study newly explored the role of RBPs across all cancer types and highlighted the role of RBP4 and RBP7 in TNBC." (PMID 41301068, 2025). "RBP4 is also identified as a biomarker for diagnosing and prognosing hepatocellular carcinoma, gastric cancer, and breast cancer." (PMID 39770478, 2024). "RBP4 enhances the metastatic potential of breast cancer tumors through direct action on cancer cells and by increasing endothelial dysfunction and vascular damage within the tumor." (PMID 38129891, 2023).
breast carcinoma (continued). "We confirmed that the expression of KIF4A, UBE2C and COL11A1 was distinctly increased in BC specimens compared with normal breast specimens, while the expression of SFRP1, SAA1 and RBP4 was distinctly decreased in breast cancer specimens." (PMID 35646102, 2022). "Intriguingly, bioinformatic analyses demonstrated a lower expression of RBP4-mRNA in breast cancer tissues, and lower RBP4 indicated poorer overall survival of breast cancer patients." (PMID 36632438, 2022). "Higher plasma levels of RBP4 were observed in breast cancer patients with metastatic tumors than in healthy donors and patients with nonmetastatic cancer." (PMID 32156052, 2020). "RBP4 enhances the metastatic potential of breast cancer tumors through a direct effect on cancer cells and through increased endothelial dysfunction and impairment of blood vessels within the tumor." (PMID 32156052, 2020). "Although several studies have presented the analysis of the effect of RBP4 on several types of cancers, only one study has shown such research on patients with breast cancer." (PMID 32156052, 2020). "The plasma level of RBP4 in patients with breast cancer was significantly higher in specimens from metastatic cancers (lymph nodes or disseminated metastases) than those in healthy volunteers and patients without diagnosed metastases." (PMID 32156052, 2020). "The serum levels of RBP4 were significantly higher in patients with breast cancer than that in the healthy control group (33.77±9.92 vs. 28.77±6.47μg/ml, P < 0.05)." (PMID 28002423, 2016). "Our results suggested that serum RBP4 levels are positively correlated with BMI and TG among healthy control group, serum RBP4 concentrations were positively correlated with BMI among patients with breast cancer." (PMID 28002423, 2016). "Among breast cancer patients, serum RBP4 levels were significant higher in patients with ER or PR negative than those in patients with ER or PR positive." (PMID 28002423, 2016). "After adjustment for age and menarche age, the OR of breast cancer is 2.44 in individuals with the highest RBP4 tertile, when compared with individuals with the lowest RBP4 tertile(P <0.05)." (PMID 28002423, 2016). "We compute the odds ratios (ORs) and 95% confidence intervals (CIs) for breast cancer by tertile of RBP4 levels, which is defined by the serum RBP4 levels of healthy subjects." (PMID 28002423, 2016). "Studies also showed that RBP4 were overexpressed in the head and neck squamous cell carcinoma, breast cancer, and colon adenocarcinoma tissues." (PMID 25250314, 2014). "Elevated serum levels of RBP4 have been associated with an increased risk of breast cancer, with higher levels found in patients with negative progesterone or estrogen receptors compared to those with positive receptors." (PMID 41301068, 2025). "Conversely, other studies suggest that RBP4 may inhibit tumor growth, as low RBP4 expression in breast cancer tissues has been positively correlated with better prognosis." (PMID 41301068, 2025). "Additionally, RBP4 was reported to enhance the metastatic potential of breast cancer through both direct effect on cancer cells and through impairing endothelial blood vessels within the tumor." (PMID 36632438, 2022). "The leaky blood vessels of 4T1 tumors result in a higher degree of permeability reflected in higher Ktrans values, which was similarly found in a study evaluating the role of retinol-binding protein 4 in the metastatic potential of breast cancer, also using 4T1 and 67NR as tumor models." (PMID 36408159, 2022). "In head and neck cancer, breast cancer, hepatocellular carcinoma and other cancers, serum RBP4 levels were significantly reduced, and the decrease might be caused by methylation." (PMID 34889069, 2022).
breast carcinoma (continued). "The aim of our studies was to explain the role of RBP4 protein in the growth and metastatic spread of two murine breast cancer isogenic cell lines (derived from a single tumor of BALB/c mouse); metastatic 4T1 and nonmetastatic 67NR, representing basal-like and luminal-like phenotype, respectively." (PMID 32156052, 2020). "After adjusted for age,miscarriage history, menopause status and menarche age, there was significantly positive correlation between serum RBP4 level and BMI in breast cancer group(P < 0.05), while circulating RBP4 levels were significantly correlate with BMI and TG in control group." (PMID 28002423, 2016). "We analyzed the mean of serum RBP4 levels in the classified breast cancer patients." (PMID 28002423, 2016). "Correlation between Serum RBP4 and clinical characteristics in breast cancer patients." (PMID 28002423, 2016). "Stratified analyses of Odds ratios and 95% confidence intervals of breast cancer with RBP4." (PMID 28002423, 2016). "Therefore, in the future prospective cohort studies on serum RBP4 and breast cancer should be designed to further ascertain this relationship." (PMID 28002423, 2016). "However, the role of RBP4 in breast cancer remains controversial." (PMID 41301068, 2025). "However, the evidences on associations of serum RBP4 with breast cancer risk have not been well studied." (PMID 28002423, 2016). "However, no studies have investigated the relationship between serum RBP4 levels and breast cancer risk." (PMID 28002423, 2016). "We infer that serum RBP4 level may be correlated with breast cancer prognosis." (PMID 28002423, 2016). "Due to a lack of detailed data on dietary information, the possible influence of diet on the association of serum RBP4 with breast cancer could not be adequately evaluated." (PMID 28002423, 2016). "However, no studies have investigated the relationship between RBP4 and breast cancer risk." (PMID 28002423, 2016). "Notably, we demonstrate that RBP4 and RBP7 have particularly important clinical relevance in breast cancer." (PMID 41301068, 2025). "Cox analysis identified RBP4 as a protective gene in kidney renal papillary cell carcinoma (KIRP), liver hepatocellular carcinoma (LIHC), and mesothelioma (MESO), while RBP7 exhibited protective effects in breast cancer (BRCA) and uveal melanoma (UVM)." (PMID 41301068, 2025). "Retinol-binding protein 4 (RBP4) is a monomeric-binding protein belonging to the lipocalin protein family, which has been reported to be dysregulated in several malignancies such as breast cancer and lung cancer." (PMID 36632438, 2022). "We analyzed the role of RBP4 in metastasis of breast cancer in patients and in mice bearing metastatic 4T1 and nonmetastatic 67NR mammary gland cancer." (PMID 32156052, 2020). "For breast cancer patients, patients with PR or ER negative displayed significantly higher serum RBP4 levels than those with PR or ER positive." (PMID 28002423, 2016). "In summary, the results from this study show that higher circulating levels of RBP4 are associated, independent of BMI, lipids, FBG and other potential risk factors, with an increased risk of breast cancer." (PMID 28002423, 2016). "Metastatic breast cancer patients also show higher RBP4 levels than non-metastatic patients." (PMID 41301068, 2025).
Impaired glucose tolerance (17 papers, 2012 to 2025). An abnormal resistance to glucose, i.e., a reduction in the ability to maintain glucose levels in the blood stream within normal limits following oral or intravenous administration of glucose. "Clinical studies have shown that individuals with impaired glucose tolerance and T2DM have elevated circulating RBP4 levels, which was inversely associated with insulin sensitivity." (PMID 37312059, 2023). "Higher RBP4 levels have been reported in human subjects with impaired glucose tolerance compared to those with normal glucose tolerance." (PMID 30651745, 2019). "In addition, the literature has reported that the ratio of circulating RBP4 to retinol is greater in patients with impaired glucose tolerance and T2DM than in healthy individuals." (PMID 38520616, 2024). "The researcher discovered that circulating RBP4 levels were correlated with the degree of IR in patients, including obese patients, impaired glucose tolerance patients, and type 2 diabetics as well in normal participants with a family history of these diseases." (PMID 36670387, 2023). "Furthermore, animal studies revealed that elevated levels of liver-derived RBP4 do not cause impaired glucose tolerance in mice, indicating that circulating RBP4 concentrations may not be responsible for impaired glucose homeostasis." (PMID 38520616, 2024). "Moreover, the levels of plasma RBP4 are significantly elevated in HUA rats and patients with HUA, which is accompanied by impaired glucose tolerance and reduced insulin sensitivity in HUA rats." (PMID 34177800, 2021).
hypertriglyceridemia (16 papers, 2012 to 2023). A laboratory test result indicating elevated triglyceride concentration in the blood. "The rs34571439 variant (RBP4 gene) has been implicated in hypertriglyceridemia and childhood obesity." (PMID 36983642, 2023). "A mendelian randomization study found similar results showing that the number of RBP-4 variants were associated with increased risk of hypertriglyceridemia." (PMID 32516964, 2020). "Previous studies have shown that RBP4 is associated with fatty acid metabolism and there is a strong association between RBP4 and hypertriglyceridaemia." (PMID 31051472, 2019). "The most significant findings of our study are the associations between the levels of RBP4 and hypertriglyceridemia, as well as low HDL cholesterol levels (in the multivariate analysis)." (PMID 29524177, 2018). "The results showed that after adjustment for age and gender, individuals with RBP4 levels in the highest tertile had 3.7 times higher risk of developing hypertriglyceridemia than those in the lowest tertile (OR = 3.71, 95% CI = 1.42–9.73)." (PMID 29747616, 2018). "After adjustment for age and gender, the risk of hypertriglyceridemia was 3.7 times greater (95% CI =1.42–9.73, p = 0.008) in the highest RBP4 tertile as compared to the lowest tertile." (PMID 29747616, 2018). "RBP4 was also positively associated with some of the MetS components, including hypertriglyceridemia, reduced HDL cholesterol, elevated LDL cholesterol and hyperglycemia." (PMID 24559154, 2014). "In addition, the risk of hypertriglyceridemia was approximately 4-fold greater in subjects with high serum RBP4 and TTR levels and HOMA-IR values." (PMID 29747616, 2018). "Hypertriglyceridemia was most strongly associated with elevated plasma RBP4 levels." (PMID 29524177, 2018). "Other factors that positively correlated with RBP4 levels after sex adjustment were hypertriglyceridemia and a higher systolic BP." (PMID 29524177, 2018). "Additionally, RBP4 levels of patients with hypertriglyceridemia or hypercholesterolemia were significantly higher than patients with normal TG or TCH in females." (PMID 31956345, 2020). "Hypertriglyceridemia as a component of MS is most significantly related to RBP4 concentration." (PMID 29524177, 2018). "In elderly men, RBP4 levels correlated with hypertriglyceridemia and prior cerebrovascular disease." (PMID 25142320, 2014). "The ORs (95% CIs) for the comparisons of the extreme quartiles of RBP4 were 3.46 (2.87, 4.42) for MetS, 5.92 (4.47, 8.02) for hypertriglyceridemia, 1.42 (1.11, 1.68) for reduced HDL cholesterol, 1.87 (1.48, 2.36) for central obesity and 2.74 (2.15, 3.36) for hyperglycemia (all P < 0.001)." (PMID 24559154, 2014). "Taken as a whole, these data suggest that RBP4 may play a role in the pathophysiology of hypertriglyceridemia in insulin-resistant states." (PMID 24223837, 2013). "Additionally, RBP4 levels of the patients with hypertriglyceridemia or hypercholesterolemia were significantly higher than patients with normal TG or TCH (59.36 ± 16.82 mg/L vs. 46.92 ± 14.76 mg/L, P = 0.029, and 60.66 ± 19.74 mg/L vs. 47.36 ± 13.88 mg/L, P = 0.028)." (PMID 31956345, 2020).
COVID-19 (14 papers, 2021 to 2025). A disease caused by infection with severe acute respiratory syndrome coronavirus 2. "RBP4 was associated with lower COVID-19 susceptibility using the Wald ratio (OR: 0.83, 95% CI: 0.72–0.95, P: 0.0072)." (PMID 38671384, 2024). "Here, we assessed the association between the development and severity of COVID-19, and retinol and RA signaling pathway, by MR, utilizing alleles as proxies for the genetically predicted circulating status of retinol, RBP4, RDH16 and CRABP1." (PMID 38671384, 2024). "The associations between RBP4 with COVID-19 hospitalization (OR: 0.76, 95% CI: 0.58-1.00, P: 0.0505) and severity (OR: 0.86, 95% CI: 0.73–1.02, P: 0.0788) were not significant." (PMID 38671384, 2024). "In the present study, based on the available GWAS, we investigate the causal effect of COVID-19 and retinol, RBP4, RDH16 and CRABP1 through two-sample MR approach." (PMID 38671384, 2024). "Lower levels of adiponectin and RBP4 have been associated with higher risk of severe COVID-19 and adverse outcomes." (PMID 37629176, 2023). "This prospective, multicenter, observational, cross-sectional study examined RBP4 (enzyme-linked immunosorbent assay) and vitamin A plasma levels (high-performance liquid chromatography) in COVID-19 patients, including 59 hospitalized patients." (PMID 35631143, 2022). "RBP4 was associated with COVID-19 susceptibility using the Wald ratio (OR: 0.83, 95% CI: 0.72–0.95, P: 0.0072) at a significance threshold (P < 5 × 10− 8), but the association was not significant (OR: 0.96, 95% CI: 0.91–1.02, P: 0.2693) at a liberal significance threshold (P < 5 × 10− 6)." (PMID 38671384, 2024). "This MR study also found that the inverse correlation of RBP4 with COVID-19 susceptibility, which may indirectly support a causal link between VA and COVID-19." (PMID 38671384, 2024). "The authors concluded that plasma levels of RBP4 are significantly reduced during acute inflammation in critically ill COVID-19 patients." (PMID 40881125, 2025). "A prior investigation showed a significant correlation between elevated inflammatory markers, particularly CRP, and lower plasma RBP4 levels in critically ill COVID-19 patients." (PMID 40881125, 2025). "The results of the current study demonstrate a significant prevalence of suboptimal vitamin A intake and insufficient RBP4 concentrations in COVID-19 outpatients." (PMID 38541764, 2024). "RBP4 and VA levels were significantly decreased in patients hospitalized with COVID-19 during the acute phase of infection compared to patients recovering after a mild course of the disease." (PMID 38671384, 2024). "We found evidence of possible causal association of retinol, RBP4, RDH16 and CRABP1 with the susceptibility, hospitalization and severity of COVID-19." (PMID 38671384, 2024). "In MR analysis between RBP4 and COVID-19 hospitalization, rs112357560 was deleted due to horizontal pleiotropy in MR-PRESSO." (PMID 38671384, 2024). "We conducted a two-sample Mendelian randomization (MR) study to assess the associations of retinol, retinol binding protein 4 (RBP4), retinol dehydrogenase 16 (RDH16) and cellular retinoic acid binding protein 1 (CRABP1) with COVID-19 in European population." (PMID 38671384, 2024). "The RBP4/vitamin A molar ratio was increased in hospitalized COVID-19 patients during the acute phase of illness." (PMID 35631143, 2022). "In a subgroup analysis, we demonstrated significantly reduced RBP4 levels in critically ill COVID-19 patients compared to convalescent patients." (PMID 35631143, 2022). "This study investigated the connection between RBP4 and vitamin A plasma levels with inflammatory markers and the progression of COVID-19 (critical, severe, moderate) in the acute phase of the disease in hospitalized patients and in convalescent patients." (PMID 35631143, 2022).